CRP (C-reactive protein)
Diseases named in the same sentence as CRP in open-access papers (continued):
Sharing a sentence is not in itself a finding about the gene and the disease.
Sepsis (continued). "In view of these statements, it seems quite unlikely that neonates in this study with serial normal CRP levels e.g. < 10 mg/L, did have sepsis." (PMID 19152691, 2009). "In the present study, irritability, feeding difficulties and a marked rise in CRP were important in establishing the diagnosis of sepsis in the newborn." (PMID 19152691, 2009). "In our study, the changes in the systemic levels of IL-6, IL-1-beta, IL-10, and CRP were unable to discriminate survivors from non survivors during the first week of severe sepsis." (PMID 19718443, 2009). "Previously, authors have operated with different cut off points for CRP in the diagnosis of neonatal clinical septicemia." (PMID 19152691, 2009). "If the effect to belong to a latent condition of sepsis would be removed, the effects to the CRP, PCT and DD would have a completely random distribution in the study population." (PMID 18284667, 2008). "There was a significant association between mortality and the presence of sepsis, coagulopathy, and higher mean PRISM score, leucocytosis, leucopenia, hyperbilirubinemia, and CRP levels." (PMID 19742257, 2008). "Our results show the higher sensitivity and specificity of eosinopenia compared with the CRP level in the diagnosis of sepsis on admission to the ICU." (PMID 18435836, 2008). "The aim of this study was to determine the value of serum levels of IL-6, IL-8 and C-reactive protein (CRP) as predictors for sepsis or prolonged fever in children with fever and neutropenia due to chemotherapy at the start of a febrile episode." (PMID 18321393, 2008). "As authors stated “CRP, IL-6 and LBP appear to be superior to PCT as diagnostic markers for infection and sepsis in patients." (PMID 19578505, 2008). "We have also shown that CRP, lipopolysaccharide-binding protein (LBP), and IL-6 were better diagnostic markers for infection and sepsis than procalcitonin (PCT) in the same cohort of patients." (PMID 17346334, 2007). "Nevertheless, this study poses novel considerations based on simple monitoring of dynamic changes of blood CRP levels in children with sepsis, with results that prove worthy of further investigation." (PMID 17598889, 2007). "CRP levels reach lower values in patients with SIRS than in those with sepsis, septic shock, or MODS." (PMID 17598889, 2007). "Using a cut off level of 38 mg/l, CRP had a sensitivity of 79.7% and a specificity of 57.9% in diagnosing sepsis/severe sepsis." (PMID 16569262, 2006). "• In a cohort of patients with less severe community-acquired infections, CRP, IL-6 and LBP appear to be superior to PCT as diagnostic markers for sepsis." (PMID 16569262, 2006). "IL-6, lipopolysaccharide-binding protein and C-reactive protein performed best in distinguishing between systemic inflammatory response syndrome and sepsis, with an area under the curve larger than 0.84 (P < 0.01)." (PMID 16569262, 2006). "The decrease in CRP preceded clinical resolution of sepsis and was more likely to occur in patients with less severe sepsis than in those with severe sepsis or septic shock." (PMID 16956405, 2006). "We studied the ability of procalcitonin, lipopolysaccharide-binding protein, IL-6 and C-reactive protein to identify patients with infection and sepsis." (PMID 16569262, 2006). "Yentis and colleagues demonstrated that a decrease in CRP by 25% or more from the previous day's level was a good indicator of resolution of sepsis, with a sensitivity of 97%, a specificity of 95% and a predictive value of 97%." (PMID 16956405, 2006). "They compared PCT and CRP at different SOFA scores during the course of sepsis and multiple organ dysfunction syndrome." (PMID 16956405, 2006). "Our data were obtained in the first 24 hours of ICU admission or of sepsis, thus, the relation between CRP and hypofibrinolysis appeared very quickly." (PMID 15456513, 2004).
Sepsis (continued). "Several authors reported significantly higher CRP levels in femoral blood in deaths related to myocarditis and sepsis than in ischemic sudden deaths, suggesting that CRP may assist in distinguishing inflammatory from ischemic mechanisms." (PMID 41596321, 2026). "Furthermore, the sepsis group exhibited significantly elevated levels of IL-6, CRP, PCT, and SOFA scores (P<0.05), lower lymphocyte counts (P = 0.017), and more pronounced coagulation abnormalities, hypoalbuminemia, and increased cardiac/renal markers." (PMID 41988187, 2026). "In the multivariable model including age, sex, ethnicity, ascites, esophageal varices, INR, creatinine, neutrophil-to-lymphocyte ratio, and CRP, baseline serum creatinine was the only independent predictor of sepsis (adjusted OR 1.58 per 1 mg/dL increase, 95% CI 1.08-2.33, p = 0.01)." (PMID 42075180, 2026). "Increased risks were also observed for sepsis (HR 1.76; p = 0.001), intensive care unit admission (HR 1.67; p = 0.004), urinary tract infection (HR 1.47; p < 0.001), and elevated C-reactive protein levels (HR 1.49; p = 0.002)." (PMID 41939182, 2026). "Similarly, CRP demonstrates variable performance with AUC values of 0.67 in general sepsis populations and up to 0.945 in pediatric cases, yet its specificity can be as low as 55% in some analyses." (PMID 41567194, 2025). "One registrar cited a situation in which CRP was used diagnostically early on: "The only thing that made us think about sepsis was that we had some high CRP and we couldn't get any other any other reason for his altered mental state." (PMID 40099102, 2025). "Patients with normal CRP were more likely to undergo successful surgery, whereas elderly, frail patients with sepsis may have poor outcomes." (PMID 41503295, 2025). "Higher CRP and WBC levels were associated with increased odds of sepsis." (PMID 40142700, 2025). "Although widely available and inexpensive, CRP lacks specificity and can be elevated in a range of non-infectious conditions, limiting its standalone diagnostic value in sepsis." (PMID 40804855, 2025). "While CRP and procalcitonin are widely used in sepsis management, they reflect hepatic acute-phase responses and may lag behind the immediate cytokine storm that characterizes early severe disease." (PMID 41439926, 2025). "We did not collect data on inflammatory markers such as C-reactive protein or procalcitonin as they are not included in any sepsis diagnostic criteria or risk stratification criteria." (PMID 41093338, 2025). "CRP and procalcitonin have been used as clinical sepsis biomarkers for years." (PMID 40478618, 2025). "A recent meta-analysis of 60 studies involving the assessment of 99 biomarkers as independent prognostic factors for mortality in sepsis showed that isolated measurements of C-reactive protein, procalcitonin, interleukin-6, and presepsin at baseline did not help predict mortality in these patients." (PMID 40172393, 2025). "Whereas plasma ACE2 did not predict mortality, CRP and creatinine were only weak predictors (AUC < 0.6), as were vital signs (AUC 0.57–0.67), underlining the complexity of risk prediction in sepsis patients." (PMID 40268960, 2025). "P-SEP may be a useful biomarker in the ED because plasma P-SEP levels are more rapidly elevated than those of PCT or CRP in patients with sepsis." (PMID 41153306, 2025). "Similarly, the presence of sepsis (as defined by Goldstein’s criteria) was equally poorly discriminative (AUC = 0.51; 95% CI = 0.47 to 0.55), as was CRP concentration (AUC = 0.52; 95% CI = 0.47 to 0.57)." (PMID 40569209, 2025). "However, CRP has limited value in discriminating bacterial infections and predicting severity of sepsis." (PMID 41225969, 2025). "CRP preoperative values were significantly higher in the sepsis group (AUC:0.71, 95%CI: 0.61–0.81)." (PMID 40685448, 2025). "This meta-analysis demonstrated that the diagnostic accuracy of RETN levels for sepsis in neonates and children was not inferior to that of CRP levels." (PMID 40416430, 2025).
Sepsis (continued). "The ability of calprotectin to diagnose sepsis remained inferior to CRP in all subgroups." (PMID 40319081, 2025). "IL-6, in conjunction with other biomarkers such as C-reactive protein (CRP) and procalcitonin, may improve the accuracy of sepsis diagnosis and help guide antibiotic therapy." (PMID 40242671, 2025). "In sepsis and pneumonia, MR-proADM has consistently emerged as one of the strongest predictors of mortality, outperforming classical inflammatory markers such as CRP and procalcitonin." (PMID 41155371, 2025). "When combined with CRP and PCT, the NRBC count improved the risk prediction accuracy (AUC increased from 0.746 to 0.956), enabling more precise clinical assessment in pediatric sepsis management." (PMID 40895306, 2025). "The slow rise in CRP levels also limits its utility for early sepsis identification." (PMID 39858517, 2025). "PCT and CRP continue to be the most frequently assessed biomarkers for patients with sepsis." (PMID 39266629, 2025). "Notably, the synergistic application of sTREM-1, CRP, and leukocytosis achieved a 100% predictive probability for sepsis, highlighting the additive value of multiparameter analysis." (PMID 40806505, 2025). "Further studies may clarify the role of CRP in predicting inflammation or sepsis in the perioperative management of burn patients and support the development of more precise clinical guidelines." (PMID 40507966, 2025). "While IPF is widely applied in the clinical assessment of thrombocytopenia, its diagnostic relevance has also been recognized in inflammatory and infectious diseases, including sepsis in adults, where it may offer improved accuracy over CRP and PCT." (PMID 40723124, 2025). "CRP is an important biomarker for assessing the severity of hepatitis and serves as an early warning for the severity of acute hepatitis and the possibility of sepsis." (PMID 39996800, 2025). "In sepsis, combining CRP and cfDNA measurements could enhance early diagnosis and prognostic assessment." (PMID 40282303, 2025). "Published evidence the last five years exists for heparin-binding protein (HBP), monocyte distribution width (MDW), interleukin-10 (IL-10), presepsin, procalcitonin and C-reactive protein (CRP) for early sepsis diagnosis; procalcitonin is the most well-studied biomarker for antibiotic guidance." (PMID 40685448, 2025). "With current biomarkers like procalcitonin and CRP offering limited specificity and prognostic power, there is a growing demand for precision tools to characterize the molecular events that define sepsis onset and progression." (PMID 40724897, 2025). "MPI, C-reactive protein, and sepsis emerged as additional significant predictors of mortality." (PMID 40849853, 2025). "The level of CRP was significantly higher in GNB- than in GPB-infected sepsis patients." (PMID 41040784, 2025). "Moreover, due to the dynamic and rapid nature of the inflammatory response observed in these diseases, this review focuses on the effect of acute conditions, such as myocardial infarction, sepsis, and physical exercise, on CRP and cfDNA levels." (PMID 40282303, 2025). "Therefore, illness severity was evaluated using available objective markers, such as lactate, CRP, creatinine, and the presence of organ failure or sepsis." (PMID 40507678, 2025). "Similarly, our findings identified T2DM-related factors—such as elevated CRP, FPG, and BMI—as independent sepsis risk predictors." (PMID 40761819, 2025). "The predictive value of CRP for sepsis-related mortality remains debated." (PMID 39825283, 2025). "•CRP shows high sensitivity but low specificity for adult sepsis diagnosis." (PMID 41429071, 2025). "Animals were randomized into four groups: control, vitamin E, sepsis, and sepsis plus vitamin E. Serum oxidative stress markers, thiol-disulfide parameters, and inflammatory mediators, including C-reactive protein, interleukin-40, and tumor necrosis factor-alpha, were measured." (PMID 41196905, 2025).
Sepsis (continued). "Ten studies reported C-reactive protein levels, and the pooled results suggested that the combination of THCQ with CT was superior to CT alone in lowering CRP levels in sepsis patients (MD = −9.82 mg/L, 95% CI: −13.98 to −5.66; nine trials, 596 participants, I2 = 84%)." (PMID 40963685, 2025). "We observed increased values of inflammatory markers in patients with sepsis: the mean value of C-reactive protein was 195 ± 121.90 in group 1 and 98.32 ± 97.96 in group 2—a statistically significant difference (p < 0.0001)—the same results for interleukin 6 (p < 0.0001)." (PMID 40564087, 2025). "This could be explained by the late onset of CRP rising levels: within 6–8 h of infection and peaks at 24 h of the sepsis course." (PMID 40224545, 2025). "The integration of multiple biomarkers, including MDW, CRP, and PCT, may enhance the diagnostic process, offering a more comprehensive approach to sepsis detection." (PMID 41303127, 2025). "Using Gal-9, sTREM-1, sCD25, CRP, and lactate, multivariable Cox proportional hazards model analysis was performed to identify the risk factors for 30-day mortality among the overall study population, including NIOF, sepsis, and septic shock." (PMID 41225969, 2025). "Therefore, while CRP is regarded as a primary biochemical marker for sepsis due to its rapid rise in response to inflammation, its lack of specificity limits its diagnostic value." (PMID 40282303, 2025). "MiRNA-146a showed a significant positive correlation with CRP levels in the sepsis group." (PMID 41300689, 2025). "CRP is an acute-phase reactant elevated in sepsis, providing insights into inflammatory severity." (PMID 41281283, 2025). "Therefore, we aimed to build a prediction model for sepsis by combining sTREM-1, CRP, and leukocyte counts through a BN." (PMID 40806505, 2025). "PTX3 levels increased in patients experiencing severe sepsis, irrespective of qSOFA, were associated with bacterial infections, and correlated with pro‐inflammatory cytokines and CRP." (PMID 40722110, 2025). "Furthermore, vitamin D supplementation notably improved the sepsis scores and decreased high-sensitivity C-reactive protein (hs-CRP) levels at 3, 7, and 10 days of treatment (p < 0.05)." (PMID 40150674, 2025). "With regard to the other markers, the median high-sensitivity CRP value in the group of patients with AHF was 2.08 mg/dL while the median value in the AHF/sepsis group was 15.57 mg/dL and the median value of high-sensitivity CRP in the group of patients with sepsis was 6.45 mg/dL." (PMID 40310380, 2025). "As CRP levels are typically elevated in sepsis, this study aimed to investigate whether sLOX-1 levels increase in parallel." (PMID 39948564, 2025). "Additionally, this study demonstrated significant correlations between resistin, S100A8/A9, CRP, and IL-6 in sepsis patients." (PMID 40568710, 2025). "In the sepsis model, pretreatment with AZ+PA alleviated clinical symptoms, maintained body weight, and significantly improved hematological parameters, reducing WBCs and CRP levels." (PMID 40871061, 2025). "We recommend improving neonatal sepsis management by increasing funding and strategic investments in healthcare infrastructure and routine availability of blood cultures and biomarkers such as CRP and procalcitonin." (PMID 40535411, 2025). "Although CRP is widely used as a marker of inflammation, its levels are elevated in a range of inflammatory conditions, and its low specificity limits its utility in diagnosing sepsis." (PMID 40282303, 2025). "However, recent reports in severe sepsis and bacterial pneumonia have shown that CRP levels in severe bacterial infections frequently exceed 85–100 mg/L, overlapping with the high values observed in our melioidosis cohort." (PMID 41010302, 2025). "We recently discovered that the EGFR ligand, amphiregulin, could identify a cohort of infants with sepsis, even when CRP was low, identifying it as a potentially adjunctive biomarker for early infection." (PMID 41063987, 2025).
Sepsis (continued). "In a study in which sepsis was diagnosed according to the Sepsis Guideline criteria and no pathogenic factors were specified, it was reported that CRP, procalcitonin, and presepsin were not sufficient to predict mortality in the ICU18." (PMID 40172393, 2025). "To understand if CRP recognizes any capsules of Gram-negative bacteria, we first tested the impact of CRP deficiency on the early clearance of H. influenzae, an important etiological agent of childhood pneumonia, septicemia and meningitis." (PMID 41214213, 2025). "Additionally, sepsis patients had markedly increased median levels of CRP, PCT, and IL-6 compared to healthy controls." (PMID 40568710, 2025). "Procalcitonin, CRP, and albumin, along with baseline investigations, were sent on the day of admission (day 0), day 2 of admission, and day 7 of admission for all the children with suspected sepsis." (PMID 40351994, 2025). "The sepsis screening results were within the normal range (I:T ratio 0.15, mESR 3 mm, CRP < 3.41)." (PMID 40141433, 2025). "Calprotectin is inferior to CRP as a diagnostic marker of sepsis at ICU admission, and our findings do not support using calprotectin for this purpose." (PMID 40319081, 2025). "Initial laboratory investigations revealed mild leukocytosis (WBC 10.2 × 109/L), mild acute kidney injury (creatinine 187 μmol/L, urea 11.7 mmol/L), hyponatremia (sodium 128 mmol/L), elevated lactate (4 mmol/L) likely due to sepsis, and high C-reactive protein (CRP) (283 mg/L)." (PMID 40062146, 2025). "CRP is a classic acute phase-reactive protein that rises rapidly within 6–12 h of the onset of inflammation, making it a sensitive marker for monitoring the dynamics of the inflammatory response in sepsis." (PMID 41393152, 2025). "Pancreatic stone protein is demonstrated to have an AUC = 0.694 for sepsis prediction in patients with intra-abdominal infection and has an excellent diagnostic value for sepsis patients in combination with CRP that also outperforms NET-related markers and their combination with CRP." (PMID 40731775, 2025). "Fever, obstructive symptoms, signs of peritonitis, sepsis and shock, older age, evidence of portal venous gas on CT, leukocytosis, elevation of C-reactive protein, lactic acidosis, are worrisome features and poor prognostic factors necessitating surgical management." (PMID 41416340, 2025). "Introducing a broader range of biomarkers and clinical indicators, encompassing PCT and CRP, might refine sepsis prognosis accuracy." (PMID 41432366, 2025). "However, we also evaluated episodes of high CRP, which we consider to reflect platelet-consuming morbidities and established risk factors for severe ROP such as NEC, sepsis, other infections and inflammatory conditions." (PMID 39702768, 2025). "Moreover, leukocyte analysis was found to be superior in comparison to CRP measurements in early discrimination of those trauma patients prone to develop sepsis." (PMID 40471324, 2025). "Early identification of high-risk patients remains a critical challenge in sepsis management, and while traditional biomarkers such as procalcitonin (PCT) and C-reactive protein (CRP) are widely used, they have limited predictive value for disease progression and outcomes." (PMID 40666706, 2025). "Interestingly, while CRP initially emerged as the strongest predictor of sepsis based on univariate logistic regression and ROC analysis (AUC = 0.9583), it lost statistical significance after adjustment for age, sex, BMI, and comorbidities (p = 0.147)." (PMID 41153764, 2025). "Moreover, our results also provide evidence that sivelestat sodium can significantly improve inflammatory indicators (including IL-6, PCT, CRP) and oxygenation function (PaO2/FiO2 ratio) in patients with sepsis complicated with ARDS." (PMID 40842872, 2025).